GRK6 (G protein-coupled receptor kinase 6)
Description:
Specifically phosphorylates the activated forms of G protein-coupled receptors. Such receptor phosphorylation initiates beta-arrestin-mediated receptor internalization, and signaling events leading to their desensitization. Seems to be involved in the desensitization of D2-like dopamine receptors in striatum and chemokine receptor CXCR4 which is critical for CXCL12-induced cell chemotaxis. Phosphorylates rhodopsin (RHO) (in vitro) and a non G protein-coupled receptor: LRP6 during Wnt signaling (in vitro).
Synonyms: GPRK6
Tractability: Small molecule: a structure with a bound ligand is known; a high-quality ligand is known; it has a high-quality binding pocket; it belongs to a druggable protein family. Antibody: its Gene Ontology location is reachable by antibodies, with high confidence. PROTAC: ubiquitination databases record sites on it; its protein half-life has been measured; a small molecule that binds it is known.
Target class: AGC protein kinase GRK family; Kinase; AGC protein kinase group; AGC protein kinase GRK subfamily; Enzyme; Protein Kinase
Gene: Protein-coding gene on chromosome 5 (177,403,204 to 177,442,901, forward strand). Ensembl gene ENSG00000198055.
Subcellular location: Membrane
Subcellular location (Human Protein Atlas): Mitochondria
Pathways (Reactome):
Signal Transduction: G alpha (s) signalling events
Gene Ontology:
Molecular function: beta-adrenergic receptor kinase activity; G protein-coupled receptor kinase activity; protein binding; ATP binding; protein kinase activity; protein serine/threonine kinase activity
Biological process: desensitization of G protein-coupled receptor signaling pathway; G protein-coupled receptor signaling pathway; regulation of G protein-coupled receptor signaling pathway; regulation of signal transduction; signal transduction
Cellular component: membrane; cytoplasm; plasma membrane
Genetic constraint (gnomAD): Loss-of-function variants: 37 observed, 80.58 expected, observed/expected ratio (o/e) 0.46, 90% interval 0.35 to 0.6. The upper end of that interval is the gene's LOEUF score, 0.6, which puts it in group 2 of 6, group 1 being the genes least tolerant of losing a copy. Missense variants: 546 observed, 782.79 expected, observed/expected ratio (o/e) 0.7, 90% interval 0.65 to 0.75. Synonymous variants: 290 observed, 319.75 expected, observed/expected ratio (o/e) 0.91, 90% interval 0.82 to 1.
Homologues: Orthologues: dog GRK6 (98% identical), mouse Grk6 (96% identical), macaque GRK6 (96% identical), pig GRK6 (95% identical), rat Grk6 (95% identical), rabbit GRK6 (93% identical), chimpanzee GRK6 (93% identical), guinea pig GRK6 (92% identical), zebrafish grk6 (82% identical), tropical clawed frog grk6 (80% identical), Drosophila melanogaster Gprk2 (61% identical), Caenorhabditis elegans grk-1 (59% identical). Paralogues in human: GRK5 (70% identical), GRK4 (65% identical), GRK1 (46% identical), GRK7 (43% identical), GRK2 (38% identical), GRK3 (38% identical), RSKR (19% identical).
Diseases named in the same sentence as GRK6 in open-access papers:
GRK6 is named in the same sentence as 47 diseases in open-access papers, as found by Europe PMC text mining. Sharing a sentence is not in itself a finding about the gene and the disease. The quoted sentences say what the papers report.
medulloblastoma (7 papers, 2013 to 2022). A malignant, invasive embryonal neoplasm arising from the cerebellum. "Its deficiency has also been observed in medulloblastoma tissues, which led to enhanced tumor progression depending on C‐X‐C chemokine receptor 4 signaling, while GRK6 upregulation diminished C‐X‐C motif chemokine 12‐induced migration." (PMID 30984536, 2019). "For example, downregulation of GRK2, GRK3, GRK5, and GRK6 promoted tumorigenesis and metastasis in Kaposi sarcoma, basal-like breast cancer, colon cancer, and medulloblastoma." (PMID 35769816, 2022). "In a similar manner to our findings, previous studies in medulloblastoma and Lewis lung carcinoma show that when GRK6 was downregulated, migration and metastasis were increased." (PMID 34136390, 2021). "Thereafter, a new role of GRK6 in some cancer metastases was gradually revealed, such as medulloblastoma 15, multiple myeloma 14, and lung cancer." (PMID 30984536, 2019). "In addition, up- or down-regulation of GRK6 expression has been observed in patients with hepatocellular carcinoma and medulloblastoma, respectively." (PMID 36553500, 2022).
lung adenocarcinoma (6 papers, 2019 to 2024). A carcinoma that arises from the lung and is characterized by the presence of malignant glandular epithelial cells. "In the adenocarcinoma of the lung, GRK6 expression is known to be suppressed, which is associated by elevated levels of HIF1α protein expression." (PMID 36555521, 2022). "In human lung adenocarcinoma, the hypermethylation of GRK6 promoter, the knockdown of GRK6 gene or a decreased expression of GRK6 protein was shown to correlate with an enhanced metastatic potentials and poorer prognosis." (PMID 39741338, 2024). "GRK6 was found to be hypermethylated in the adenocarcinoma of the lung, and a positive methylation status, resulting in decreased GRK6 expression levels, was associated with poor survival rates." (PMID 36555521, 2022). "In contrast, downregulation of GRK6 has been suggested as a potential biomarker for predicting overall survival in patients with lung adenocarcinoma." (PMID 36553500, 2022). "The findings were further confirmed in lung adenocarcinoma samples, in which GRK6 expressions negatively correlate with HIF1α protein levels." (PMID 34136390, 2021). "This study provides evidence that GRK6 inhibition causes a decrease in VHL expression, leading to HIFα stabilisation with increased activity in lung adenocarcinoma, although the underlying mechanism merits further investigation." (PMID 34136390, 2021). "The findings were further confirmed in lung adenocarcinoma samples, in which GRK6 expression levels negatively and positively correlate with HIF1α expression (P = 0.015) and VHL expression (P < 0.0001), respectively." (PMID 34136390, 2021). "In lung adenocarcinoma cells, the GRK6 promoter is hypermethylated and GRK6 expression is repressed, which promotes cell migration and invasion." (PMID 33920915, 2021). "Our previous study suggested that GRK6 expression was significantly down-regulated in lung adenocarcinoma patients, and its level was an independent prognostic factor for overall survival." (PMID 34136390, 2021). "Tissue microarrays were used to investigate the expression and function of GRK6 in lung adenocarcinoma." (PMID 34136390, 2021). "We previously reported that GRK6 is down-regulated in lung adenocarcinoma patients, which induces cell invasion and metastasis." (PMID 34136390, 2021). "We previously reported that the expression of G protein‐coupled receptor kinase 6 (GRK6) is significantly downregulated in lung adenocarcinoma (LADC) tissues, and low expression levels of GRK6 are correlated with poor survival prognosis." (PMID 30984536, 2019). "Targeting the HIF pathway may provide new strategies for therapy in GRK6-depleted lung adenocarcinoma patients." (PMID 34136390, 2021). "Moreover, we also showed that the promoter region of the GRK6 gene was hyper-methylated in lung adenocarcinoma tissues compared to the normal tissue samples, leading to a down-regulation of GRK6 expression and in turn, inducing cell invasion and metastasis." (PMID 34136390, 2021). "Taken together, targeting the HIF pathway may provide new strategies for therapy in GRK6-depleted lung adenocarcinoma patients." (PMID 34136390, 2021). "GRK6 is of the members of the GRK family and we previously showed that GRK6 is down-regulated in lung adenocarcinoma, which is associated with malignant tumour progression, by an unknown mechanism." (PMID 34136390, 2021). "Our study showed an increase of hypoxia-induced gene expression and HIF1α expression in GRK6 knockdown cells, this suggests that GRK6 knockdown may induce EMT in lung adenocarcinoma." (PMID 34136390, 2021). "However, further understanding of the role of GRK6 in lung adenocarcinoma is required." (PMID 34136390, 2021). "Correlation analysis was performed in the TCGA lung adenocarcinoma (LUAD) (IlluminaHiseq) dataset; samples were separated into high vs. low GRK6 expression based on an unsupervised hierarchical clustering." (PMID 34136390, 2021).
lung adenocarcinoma (continued). "Thus, ablation of the GRK6-mediated repression of MMP-2 and MMP-7 may increase the invasiveness of lung adenocarcinoma cells." (PMID 33920915, 2021).
hepatocellular carcinoma (5 papers, 2017 to 2022). A malignant tumor that arises from hepatocytes. "Similarly, GRK6 has been found to be overexpressed in hepatocellular carcinoma and was linked to poor prognosis." (PMID 30984536, 2019). "A positive association was found between GRK6 and Ki-67 expression, pathological disease stage, metastasis, and survival rate in the patients with hepatocellular carcinoma, and GRK6 was hypothesized as a biomarker for the early diagnosis of hepatocellular carcinoma." (PMID 33806057, 2021).
multiple myeloma (5 papers, 2013 to 2025). "Recently, GRK6 inhibitors, GRK6-IN-1 (compound 18) and GRK6-IN-2 (compound 10a), were chemically synthesized and suppressed the cell growth of multiple myeloma cells with a 50% of inhibitory concentration (IC50) at sub-μM." (PMID 39741338, 2024). "In these cells, we initially performed GSIS assays in the absence or presence of a 4-aminoquinazoline derivative called compound 19, a GRK inhibitor that was developed as a potential therapeutic to target GRK6 in multiple myeloma (31, 31a)." (PMID 36030052, 2022). "The same group identified a selective GRK6 inhibitor based on 4-aminoquinazoline acting synergistically to bortezomib, which is a well-established treatment for multiple myeloma." (PMID 36555521, 2022). "Additionally, GRK6 is bound by heat shock protein 90 (HSP90), and its inhibition led to a distinct decline in GRK6 expression in myeloma cells." (PMID 36555521, 2022). "Similarly, GRK6 silencing in myeloma cells induced a tumor suppressor effect by inhibiting STAT3 phosphorylation and decreasing tumor cell survival." (PMID 23497290, 2013). "GRK6, a close homolog of GRK5, is considered as a possible therapeutic target for multiple myeloma." (PMID 40388590, 2025). "Furthermore, GRK6 was successfully inhibited by treatment with GF109206X in vitro, alongside to an inhibition of protein kinase C, leading to cytotoxicity in myeloma cell lines." (PMID 36555521, 2022).
Parkinson disease (5 papers, 2020 to 2024). A progressive degenerative disorder of the central nervous system characterized by loss of dopamine producing neurons in the substantia nigra and the presence of Lewy bodies in the substantia nigra and locus coeruleus. "However, GRK3 and GRK5 are upregulated in human postmortem tissue from Parkinson’s disease with dementia (PDD) patients, while GRK6 expression is not altered." (PMID 38212557, 2024).
rheumatoid arthritis (4 papers, 2013 to 2024). A chronic, systemic autoimmune disorder characterized by inflammation in the synovial membranes and articular surfaces. "In clinical and experimental settings, GRK6 downregulation is associated with chronic inflammatory diseases such as rheumatoid arthritis, chronic inflammatory bowel disease and severe inflammatory response syndrome." (PMID 36555521, 2022). "Cardiopulmonary bypass surgery results in a systemic pro-inflammatory response, initially driven by interleukin-6, which parallels the inflammatory situation in chronic diseases such as rheumatoid arthritis, and might represent a direct causal connection to the detected decrease in GRK6 expression." (PMID 36555521, 2022). "Impairment of GRK6 expression was described in chronic inflammatory diseases such as rheumatoid arthritis and this was shown to be accompanied by an imbalance of downstream signaling pathways." (PMID 36555521, 2022). "For example, GRK6 deficiency is associated with impaired desensitization and enhanced CXCR4-mediated neutrophil migration and has been implicated in the pro-inflammatory response seen in rheumatoid arthritis." (PMID 23497290, 2013).
Hypertension (3 papers, 2016 to 2024). The presence of chronic increased pressure in the systemic arterial system. "The expression of GRK6 is affected by hypertensive status and associated with hypertension‐induced complications." (PMID 27390269, 2016). "Abnormal proliferation of endothelial cells is part of the vascular remodeling in hypertension that may be related to a decrease in vascular endothelial GRK6 expression caused by miR-27a." (PMID 38961282, 2024). "However, the proof of the association between GRK6 and hypertension is still weak and needs further exploration." (PMID 38961282, 2024). "However, there are some reports on the association between GRK6 and hypertension." (PMID 38961282, 2024). "15% cyclic stretch in vitro, which mimics the pathologically increased stretch in hypertension, repressed EC GRK6 expression via paracrine control by vascular smooth muscle cells (VSMCs)." (PMID 28106155, 2017). "We also found that GRK6, the direct target of miR-27a, participated in the regulation of secreted miR-27a from VSMCs on the proliferation of ECs in hypertension." (PMID 28106155, 2017). "The present results suggest a protective role of GRK6 in ECs, and several other studies have also demonstrated a protective effect of GRKs in hypertension." (PMID 28106155, 2017). "In addition, GRK6 regulates insulin homeostasis, an abnormality which participates in the pathogenesis of hypertension." (PMID 38961282, 2024). "Therefore, we examined the roles of GRK6 in EC proliferation during hypertension and the potential mechanobiological mechanism(s) involved in this process." (PMID 28106155, 2017). "Given that increased cyclic mechanical stretch in hypertension has important roles in the hyperproliferation of ECs8, 23, we then investigated whether the increased cyclic stretch inhibited GRK6 expression and promoted EC proliferation." (PMID 28106155, 2017).
lung carcinoma (3 papers, 2019 to 2021). "In this study, the role of GRK6 in lung cancer cells showed that the loss of GRK6 expression may participate in cell migration and invasion by regulating EMT and MMPs." (PMID 30984536, 2019). "G protein-coupled receptor kinase 6 (GRK6) is expressed in various tissues and is involved in the development of several diseases including lung cancer." (PMID 34136390, 2021). "A study using GRK6 knockout (GRK6–/–) mice showed that the absence of GRK6 led to increased growth of subcutaneously injected Lewis lung cancer cells, and an increased formation of metastases formed by tail vain injected Lewis lung cancer cells." (PMID 34109182, 2021). "Furthermore, the ChIP assay was repeated in lung cancer cell lines with or without 5‐Aza‐CdR, and we found that the binding strength of C/EBPα to the GRK6 gene promoter increased significantly in the 5‐Aza‐CdR treatment group, compared with the untreated group." (PMID 30984536, 2019).
Arthritis (2 papers, 2021 to 2022). Inflammation of a joint. "Furthermore, GRK6-knockout mice were more susceptible to K/BxN serum transfer-induced arthritis than wild-type littermates, which came along with elevated IL-6 serum levels." (PMID 36555521, 2022). "Induced arthritis in rats led to a comparable decrease in GRK2 and GRK6 protein expression levels in splenocytes as well as in activated mesenterial lymph node cells." (PMID 36555521, 2022).
autoimmune disease (2 papers, 2014 to 2016). A disorder resulting from loss of function or tissue destruction of an organ or multiple organs, arising from humoral or cellular immune responses of the individual to their own tissue constituents. "Insufficient engulfment in GRK6-deficient mice resulted in the development of an autoimmune disease-like phenotype." (PMID 24597858, 2014). "However, GRK6 knockout mice show dopaminergic supersensitivity and develop autoimmune disease." (PMID 24597858, 2014).
breast carcinoma (2 papers, 2022 to 2024). "Kaplan-Meier analyses demonstrated that a higher level of GRK6 transcript is closely associated with a poorer distant metastasis-free survival probability in TNBC patients compared to patients with unclassified breast cancers s." (PMID 39741338, 2024). "Accordingly, IHC staining results indicated that GRK6 upregulation and membrane translocation probably associates with lymph node metastasis of breast cancer These findings implicate that GRK6 may act a pivotal role in the molecular mechanism underlying the metastatic progression of TNBC." (PMID 39741338, 2024). "Immunohistochemistry (IHC) staining results derived from The Human Protein Atlas database revealed that GRK6 protein expression in breast cancer tissues is higher than that in normal mammary tissues and mainly distributed in cytoplasm and cell membrane." (PMID 39741338, 2024). "Accordingly, RT-PCR results showed that GRK6 upregulation are commonly found in primary tumors compared to adjacent normal tissues derived from 11 breast cancer patients." (PMID 39741338, 2024). "We further validated these findings by performing IHC staining for GRK6 protein levels against the commercial tissue microarray of breast cancer." (PMID 39741338, 2024). "Intriguingly, primary tumors from breast cancer patients with lymph node metastasis exhibited an increased membrane-bound GRK6." (PMID 39741338, 2024). "Besides, the opposite effects of GRK3 on the CXCR4-triggered metastatic progression of breast cancer is needed to be further validated in the GRK6-promoted TNBC metastasis." (PMID 39741338, 2024). "In breast cancer, the prognostic significance of GRK6 or its role in modulating cancer metastasis remains largely unknown even though GRK2 and GRK4, not GRK3, upregulation have been found to promote tumorigenesis, migration/invasion and metastasis in breast cancer cells." (PMID 39741338, 2024). "We found that GRK6 gene expression in primary tumors derived TNBC patients is significantly (p < 0.001) higher than that of normal tissues and primary tumors derived non-TNBC patients in TCGA breast cancer database." (PMID 39741338, 2024).
colorectal cancer (2 papers, 2022 to 2023). A primary or metastatic malignant neoplasm that affects the colon or rectum. "Up-regulation of GRK6 has been associated with colorectal cancer and is considered a potential biomarker for predicting poor survival in colorectal cancer patients." (PMID 36553500, 2022). "Besides, up-regulated GRK6 level is also associated with the progression and prognosis of colorectal carcinoma, and its role in AML is worth further exploration." (PMID 38098504, 2023).
schizophrenia (2 papers, 2015 to 2021). A major psychotic disorder characterized by abnormalities in the perception or expression of reality. "There have been two studies of the genetic association of GRK6 in patients with schizophrenia." (PMID 26694375, 2015). "In young patients with schizophrenia, GRK3 had been reduced, whereas in the older schizophrenia group, GRK6 showed the greatest reduction." (PMID 34916973, 2021).
systemic lupus erythematosus (2 papers, 2014 to 2015). An autoimmune multi-organ disease typically associated with vasculopathy and autoantibody production. "We found that GRK6 expression was increased in MRL/Lpr mice, a murine model of systemic lupus erythematosus (SLE), and the autopsied spleens from SLE patients." (PMID 24597858, 2014).
WHIM syndrome (2 papers, 2009 to 2022). "In Grk6-deficient mice, the neutrophils display enhanced SDF-1/CXCL12-induced chemotaxis in vitro, and thus display some of the hematological abnormalities of patients with WHIM syndrome." (PMID 19956569, 2009).
Autoimmunity (1 paper, 2022). The occurrence of an immune reaction against the organism's own cells or tissues. "Decreased GRK6 expression levels may contribute to autoimmunity by reduced engulfment of apoptotic material." (PMID 36555521, 2022).